LDLRAD4 (low density lipoprotein receptor class A domain containing 4)
Description:
Functions as a negative regulator of TGF-beta signaling and thereby probably plays a role in cell proliferation, differentiation, apoptosis, motility, extracellular matrix production and immunosuppression. In the canonical TGF-beta pathway, ZFYVE9/SARA recruits the intracellular signal transducer and transcriptional modulators SMAD2 and SMAD3 to the TGF-beta receptor. Phosphorylated by the receptor, SMAD2 and SMAD3 then form a heteromeric complex with SMAD4 that translocates to the nucleus to regulate transcription. Through interaction with SMAD2 and SMAD3, LDLRAD4 may compete with ZFYVE9 and SMAD4 and prevent propagation of the intracellular signal.
Synonyms: C18orf1
Tractability: Antibody: UniProt predicts a signal peptide or a membrane-spanning region. PROTAC: ubiquitination databases record sites on it.
Gene: Protein-coding gene on chromosome 18 (13,216,173 to 13,652,755, forward strand). Ensembl gene ENSG00000168675.
Subcellular location: Early endosome membrane
Subcellular location (Human Protein Atlas): Vesicles
Gene Ontology:
Molecular function: protein binding; R-SMAD binding
Biological process: negative regulation of cell migration; negative regulation of epithelial to mesenchymal transition; negative regulation of SMAD protein signal transduction; negative regulation of transforming growth factor beta receptor signaling pathway
Cellular component: early endosome membrane; Golgi membrane; membrane
Genetic constraint (gnomAD): Loss-of-function variants: 7 observed, 19.74 expected, observed/expected ratio (o/e) 0.35, 90% interval 0.2 to 0.67. The upper end of that interval is the gene's LOEUF score, 0.67, which puts it in group 2 of 6, group 1 being the genes least tolerant of losing a copy. Missense variants: 311 observed, 411.53 expected, observed/expected ratio (o/e) 0.76, 90% interval 0.69 to 0.83. Synonymous variants: 152 observed, 163.35 expected, observed/expected ratio (o/e) 0.93, 90% interval 0.81 to 1.07.
Homologues: Orthologues: chimpanzee LDLRAD4 (99% identical), macaque LDLRAD4 (97% identical), rat Ldlrad4 (91% identical), mouse Ldlrad4 (90% identical), rabbit LDLRAD4 (90% identical), tropical clawed frog ldlrad4 (83% identical), dog LDLRAD4 (77% identical), pig LDLRAD4 (67% identical), zebrafish ldlrad4a (59% identical), zebrafish ldlrad4b (54% identical), Drosophila melanogaster CG5151 (22% identical). Paralogues in human: PMEPA1 (58% identical).
Diseases named in the same sentence as LDLRAD4 in open-access papers:
LDLRAD4 is named in the same sentence as 17 diseases in open-access papers, as found by Europe PMC text mining. Sharing a sentence is not in itself a finding about the gene and the disease. The quoted sentences say what the papers report.
Obesity (2 papers, 2019 to 2024). Accumulation of substantial excess body fat. "In metabolic disorders like as atherosclerosis and obesity, LDLRAD4_AS1 influences lipid metabolism pathways through the modulation of low-density lipoprotein receptor-associated protein 4 (LDLRAD4) expression." (PMID 39735547, 2024). "The present study discovered that five genes (A2BP1, TENM2, LDLRAD4, SLC9C2, and MFSD1) were associated with metabolic traits such as obesity and high blood pressures." (PMID 30547318, 2019). "Specifically, if any one of TENM2, A2BP1, LDLRAD4, SLC9C2, or MFSD1 was observed in the patients with periodontitis, obesity and blood pressure have to be treated simultaneously." (PMID 30547318, 2019). "Therefore, if any of TENM2, A2BP1, LDLRAD4, SLC9C2, and MFSD1 is detected in the patients with periodontitis, obesity and blood pressure have to be treated simultaneously." (PMID 30547318, 2019).
schizophrenia (2 papers, 2022 to 2025). A major psychotic disorder characterized by abnormalities in the perception or expression of reality. "Prior studies have demonstrated an association of genetic variants in LDLRAD4 with schizophrenia bipolar disorder, and a low-frequency variant (rs8096897) in this gene showed evidence of association with systolic blood pressure." (PMID 35234888, 2022).
breast carcinoma (1 paper, 2021). "Oncogene, LDLRAD4, which was highly expressed in multiple cancers (e.g., hepatic cancer, breast cancer and colon cancer), and KLF2, an essential transcriptional factor for MM cell survival, were also downregulated in all treated cells." (PMID 34571936, 2021).
hepatocellular carcinoma (1 paper, 2025). A malignant tumor that arises from hepatocytes. "In summary, LDLRAD4 exhibits a novel role in tumorigenesis and could potentially be targeted for the treatment of hepatocellular carcinoma." (PMID 41229886, 2025).
high blood pressure (1 paper, 2019). "Also, elevated levels of LDLRAD4, SLC9C2, and MFSD1 were observed in the patients with high blood pressure." (PMID 30547318, 2019).
leukaemia (1 paper, 2016). "Aberrations in LDLRAD4, encoding a negative regulator of transforming growth factor-β signalling, have previously not been described in leukaemia." (PMID 27265895, 2016).
periodontitis (1 paper, 2019). An acute or chronic inflammatory process that affects the tissues that surround and support the teeth. "Therefore, a significant upregulation of LDLRAD4 in periodontitis could disrupt intracellular homeostasis of calcium." (PMID 30547318, 2019). "A total 10,268 SNPs of ten targeted periodontitis genes were analyzed among 2649 SNPs in five genes (TENM2, LDLRAD4, SLC9C2, MFSD1, and A2BP1), and their statistical differences (p < 0.05) are listed." (PMID 30547318, 2019).
tumor (4 papers, 2021 to 2025). "In the realm of tumor research, LDLRAD4 presents unique research potential." (PMID 41229886, 2025). "The host gene LDLRAD4 is a negative regulator of TGF-beta signaling with roles in proliferation and apoptosis and was recently associated to negative outcome in other tumor types." (PMID 33845808, 2021).
cancer (1 paper, 2021). A tumor composed of atypical neoplastic, often pleomorphic cells that invade other tissues. "Yet, the mapped genes were highly relevant to PCa etiology and included known cancer drivers LDLRAD4, GMNN, COL1A1, CD38, PTPRN2, GTSE1 and CAMK2N1 in the risk signature and KLK2, AR, KLK3, SPDEF in the relapse signature." (PMID 33845808, 2021).
neurodevelopmental disorder (1 paper, 2024). A behavioral and cognitive disorder with onset during the developmental period that involves impaired or aberrant development of intellectual, motor, or social functions. "First, LDLRAD4 (low-density lipoprotein receptor class A domain containing 4) was one of the top hit genes associated with multiple neurodevelopmental disorders based on the analysis of copy number variations." (PMID 38965205, 2024).
LDLRAD4 also shares sentences with these, for which no sentence is quoted: atherosclerosis (1 paper); bipolar disorder (1); colon cancer (1); delirium (1); dementia (1); metabolic disorders (1); myelodysplastic syndrome (1).